SCP2D1 (SCP2 sterol binding domain containing 1)
Synonyms: C20orf79; dJ1068E13.2; HSD22
Tractability: No criterion of Open Targets' tractability assessment is met for any kind of drug.
Gene: Protein-coding gene on chromosome 20 (18,813,783 to 18,814,378, forward strand). Ensembl gene ENSG00000132631.
Gene Ontology:
Cellular component: cytosol
Genetic constraint (gnomAD): Loss-of-function variants: 8 observed, 9.74 expected, observed/expected ratio (o/e) 0.82, 90% interval 0.48 to 1.47. That is too few expected variants to judge how well the gene tolerates losing a copy. Missense variants: 199 observed, 195.76 expected, observed/expected ratio (o/e) 1.02, 90% interval 0.9 to 1.14. Synonymous variants: 66 observed, 73.33 expected, observed/expected ratio (o/e) 0.9, 90% interval 0.74 to 1.11.
Homologues: Orthologues: chimpanzee SCP2D1 (88% identical), macaque SCP2D1 (83% identical), pig SCP2D1 (83% identical), rabbit SCP2D1 (79% identical), dog SCP2D1 (74% identical), rat Scp2d1 (74% identical), mouse Scp2d1 (72% identical), Drosophila melanogaster ScpX (28% identical). Paralogues in human: SCP2 (37% identical).
Diseases named in the same sentence as SCP2D1 in open-access papers:
SCP2D1 is named in the same sentence as 4 diseases in open-access papers, as found by Europe PMC text mining. Sharing a sentence is not in itself a finding about the gene and the disease. The quoted sentences say what the papers report.
leukemia (1 paper, 2022). A malignant (clonal) hematologic disorder, involving hematopoietic stem cells and characterized by the presence of primitive or atypical myeloid or lymphoid cells in the bone marrow and the blood. "Although the SCP2D1 gene appears to display an expression in the CC tissues, this mRNA is also presented in all leukemia samples." (PMID 35627192, 2022). "These genes are LYZL6 in BC tissues and SCP2D1 and TKTL2 genes in the majority of leukemia tissues." (PMID 35627192, 2022). "The SCP2D1 gene appears to display expression in all leukemia patients but not in the BC patients." (PMID 35627192, 2022).
cancer (1 paper, 2022). A tumor composed of atypical neoplastic, often pleomorphic cells that invade other tissues. "The LYZL6 gene was expressed in a CC cell line, while the SCP2D1 (C20orf79) and TEX33 (C22orf33) genes were found to be expressed in diverse types of cancer cell lines, including CC type." (PMID 35627192, 2022).
neurodegenerative disease (1 paper, 2022). A disorder of the central nervous system characterized by gradual and progressive loss of neural tissue and neurologic function. "SCP2D1 and C20orf78 have not been reported previously to be involved with neurodegenerative disease." (PMID 35431771, 2022).
SCP2D1 also shares sentences with these, for which no sentence is quoted: chronic myeloid leukemia (1 paper).